NQO1 (NAD(P)H quinone dehydrogenase 1)
Diseases named in the same sentence as NQO1 in open-access papers (continued):
Sharing a sentence is not in itself a finding about the gene and the disease.
triple-negative breast carcinoma (5 papers, 2020 to 2022). An invasive breast carcinoma which is negative for expression of estrogen receptor (ER), progesterone receptor (PR), and human epidermal growth factor receptor 2 (HER2). "NQO1 deficient triple-negative breast cancer (TNBC) MDA-MB-231 cells were also inherently resistant to KP372-1, with or without the PARPi rucaparib." (PMID 36203459, 2022). "In conclusion, the NQO1 expression in triple-negative breast cancer cells determined their radiosensitivity and was controlled by NEAT1." (PMID 32922184, 2020). "Results showed that the protein expression and activity of NAD(P)H:quinone oxidoreductase 1 (NQO1) were upregulated in radioresistant MDA-MB-231 triple-negative breast cancer (TNBC) cells." (PMID 32922184, 2020). "However, we observed decreased NQO1 protein levels upon IFNγ treatment in three of five triple-negative breast cancer (TNBC) cell lines tested (MDA-MB-231, Hs578T, and MDA-MB-436)." (PMID 34083537, 2021). "MDA-MB-231 NQO1+, triple-negative breast cancer cells express the highest level of NQO1 protein and activity, while MDA-MB-231 NQO1− are isogenic knockouts with zero NQO1 activity." (PMID 35893874, 2022).
ulcerative colitis (5 papers, 2017 to 2025). An inflammatory bowel disease involving the mucosal surface of the large intestine and rectum. "Nrf2 antioxidant enzymes to treat ulcerative colitis are the glutamate-cysteine ligase catalytic subunit (GCLC), NAD(P)H quinone dehydrogenase 1 (NQO1), hemeoxygenase-1 (HO-1), and glutamate-cysteine ligase modifier (GCLM)." (PMID 35621954, 2022).
Anxiety (4 papers, 2020 to 2024). Intense feelings of nervousness, tension, or panic often arise in response to interpersonal stresses. "Pretreatment with NBP attenuated nociceptive sensitization, photophobia, and anxiety in the model mice, reduced expression levels of c-Fos and CGRP in the SP5C and activated Nrf2 and its downstream proteins HO-1 and NQO-1." (PMID 38565987, 2024).
brain injury (4 papers, 2018 to 2022). Acute and chronic (see also brain INJURIES, CHRONIC) injuries to the brain, including the cerebral hemispheres, CEREBELLUM, and brain STEM. "Another study showed that administration of Cur upregulated protein expression levels of both HO-1 and NQO1 in a mouse model with traumatic brain injury and ameliorated secondary issues associated with injury such oxidative stress." (PMID 31323999, 2019). "In particular, a recent study demonstrated that α-LA improved neurobehavioral function by up-regulation of Nrf2 expression and its downstream protein factors including HO-1 and quinine oxidoreductase-1 (NQO-1) after traumatic brain injury in rats." (PMID 31635029, 2019).
chronic obstructive pulmonary disease (4 papers, 2016 to 2025). A chronic and progressive lung disorder characterized by the loss of elasticity of the bronchial tree and the air sacs, destruction of the air sacs wall, thickening of the bronchial wall, and mucous accumulation in the bronchial tree. "Regarding the potential association between the NQO1 C609T polymorphism and chronic obstructive pulmonary disease (COPD), none of the patients included in our study had a COPD diagnosis." (PMID 41010895, 2025). "Lung fibroblasts gained from patients suffering from chronic obstructive pulmonary disease (COPD) express less AhR protein than patients without COPD and show decreased upregulation of NQO1 and Srxn in response to cigarette smoke extract." (PMID 27829840, 2016).
depression (4 papers, 2023 to 2026). "We analyzed the transcript levels of genes associated with depression, including crhb, mao, mc2r, pomc, and prl, as well as genes related to learning and memory, including chata, creb1a, ngfb, chrna7a, and nqo1." (PMID 40265358, 2025).
diabetic retinopathy (4 papers, 2021 to 2025). "Additionally, the protein expressions of heme oxygenase‐1 (HO‐1), glutamate‐cysteine ligase catalytic subunit (GCLC), and NAD(P)H dehydrogenase (quinone 1) (NQO1) were all significantly reduced in mice with diabetic retinopathy, and all were significantly restored by the supplement of GSP." (PMID 41409191, 2025).
lung squamous cell carcinoma (4 papers, 2019 to 2023). "In contrast, NQO1 mRNA expression levels were negatively associated with the patients’ age in ovarian serous cystadenocarcinoma, lung squamous cell carcinoma, and thyroid carcinoma." (PMID 37583897, 2023). "The classical type has the highest NQO1 mRNA expression in lung squamous cell carcinoma." (PMID 37583897, 2023). "Among above, the expression of NQO1 was higher in cancer than normal tissue (P<0.05), such as liver hepatocellular carcinoma (LIHC) and lung squamous cell carcinoma (LUSC)." (PMID 36338728, 2022). "Using control MGH7 cells, a lung squamous cell carcinoma cell line with high levels of NRF229,30, we identified a lentiviral shRNA construct (shRNA2) that was especially effective at reducing protein levels of NRF2 and the NRF2 target gene, NQO1." (PMID 31455821, 2019). "CAT, ENO1, NQO1, P4HB, and PDIA6 were unique to LUAD, while CAV1, GAPDH, GPX2, GPX3, and PDIA4 exhibited consistent trends in differential expression in both LUAD and lung squamous cell cancer, significant prognostic survival prediction (p<0.05), and excellent classification effectiveness." (PMID 37955007, 2023).
myocardial infarction (4 papers, 2016 to 2025). Gross necrosis of the myocardium, as a result of interruption of the blood supply to the area, as in coronary thrombosis. "Therefore, we explored whether Andr could block myocardial infarction induced adverse remodeling and found that Andr significantly increased the expression of Nrf2 and HO-1 and promoted the nuclear translocation of Nrf2, accompanying with upregulating the expression of Gpx, SOD, and NQO1." (PMID 31892842, 2020).
osteoporosis (4 papers, 2022 to 2026). A condition of reduced bone mass, with decreased cortical thickness and a decrease in the number and size of the trabeculae of cancellous bone (but normal chemical composition), resulting in increased fracture incidence. "Furthermore, conservation scores supported the potential pathogenicity of DYNC2H1 and NQO1, reinforcing the likelihood of their involvement in osteoporosis risk." (PMID 41515648, 2026). "Therefore, in order to mitigate the development of osteoporosis by reducing the levels of ROS, the Nrf2-mediated regulation of antioxidant enzymes such as Ho-1, Nqo1, Gclc, and Gclm should be taken into account." (PMID 38136214, 2023). "The expression of antioxidant-related proteins NRF2, HO-1, NQO1, FOXO1, and SOD-2 was increased to prevent advanced osteoporosis by inhibiting Aβ deposition and oxidative stress." (PMID 40153574, 2025).
renal carcinoma (4 papers, 2021 to 2025). A carcinoma arising from the epithelium of the renal parenchyma or the renal pelvis. "IHC analysis of TMAs of 638 renal cancers showed the correlation of the expression of NQO1 with poor survival outcome (p < .001) and high tumour grade (p < .001) and stage (p < .001) in pRCC." (PMID 39707614, 2025). "Furthermore, the downstream proteins of Nrf2, NQO1 and HO-1 were significantly enhanced in renal cancer cells under treatment with axitinib." (PMID 38953109, 2024).
rheumatoid arthritis (4 papers, 2022 to 2025). A chronic, systemic autoimmune disorder characterized by inflammation in the synovial membranes and articular surfaces. "Furthermore, fisetin suppressed adjuvant-induced oxidative damage associated with rheumatoid arthritis in rats by promoting NQO1 and Nrf2-mediated HO-1 expression." (PMID 41227350, 2025). "In rheumatoid arthritis synovial fibroblasts, calycosin significantly potentiated Nrf2 translocation by inducing p62 accumulation and Keap1 degradation to activate HO-1 and NQO1, thus suppressing IL-6 and IL-33 secretion and COX-2 mRNA and protein expression." (PMID 36358507, 2022).
thyroid cancer (4 papers, 2020 to 2025). "Therefore, these outcomes elaborated that the anticancer effect of neferine on thyroid cancer was associated with the Nrf2/HO-1/NQO1 pathway." (PMID 35794985, 2022). "Notably, it was revealed that the Nrf2/HO-1/NQO1 pathway was strongly associated with the effect of neferine on the modulation of thyroid cancer." (PMID 35794985, 2022). "Altogether, these data illustrated that the anticancer effect of neferine on thyroid cancer was involved in the Nrf2/HO-1/NQO1 pathway." (PMID 35794985, 2022). "In conclusion, the present study elucidated that neferine exerted an antitumor effect and ferroptosis-inducing effect on thyroid cancer, which was involved in the inhibition of the Nrf2/HO-1/NQO1 signaling pathway." (PMID 35794985, 2022). "The present study revealed that neferine exerted an antitumor effect and ferroptosis-inducing effect on thyroid cancer via inhibiting the Nrf2/HO-1/NQO1 pathway." (PMID 35794985, 2022). "Therefore, neferine exerted an antitumor effect and ferroptosis-inducing effect on thyroid cancer via inhibiting the Nrf2/HO-1/NQO1 pathway." (PMID 35794985, 2022). "The anticancer effect of neferine on thyroid cancer was involved in the Nrf2/HO-1/NQO1 pathway." (PMID 35794985, 2022). "Therefore, based on these results, we concluded that neferine exerted an antitumor effect and ferroptosis-inducing effect on thyroid cancer through Nrf2/HO-1/NQO1 inhibition." (PMID 35794985, 2022). "Our results confirmed that a combination of IDET and taxol reduces the mRNA expression of NQO1, HO‐1, GCLM, and FTH1 in thyroid cancer cells." (PMID 41394539, 2025). "Genes related to cytoprotection and antioxidant response (e.g., Gsta3, Gstm1, Nqo1, Gpx2), as well as the H2O2-producing gene Aox1 that is usually decreased in thyroid cancers, were all downregulated in thyroids of KO mice, as found previously in other tissues." (PMID 32961913, 2020).
allergic disease (3 papers, 2011 to 2023). An immune response that occurs following re-exposure to an innocuous antigen, and that requires the presence of existing antibodies against that antigen. "Furthermore, over-expression of phase II enzymes, including NQO1, inhibited IgE production and supports the concept that chemical up-regulation of these enzymes may represent a chemopreventative strategy in airway allergic diseases." (PMID 21752292, 2011).
amyotrophic lateral sclerosis (3 papers, 2021 to 2024). Amyotrophic lateral sclerosis (ALS) is a neurodegenerative disease characterized by progressive muscular paralysis reflecting degeneration of motor neurons in the primary motor cortex, corticospinal tracts, brainstem and spinal cord. "Additionly, NQO1 and NRF2 are known to be associated with ferroptosis in tumors, neurodegenerative diseases, amyotrophic lateral sclerosis." (PMID 37583897, 2023).
brain cancer (3 papers, 2024 to 2025). A primary or metastatic malignant neoplasm affecting the brain. "Given the fact that NQO1 is similarly overexpressed in most solid tumors of breast [V64], lung, prostate colon, pancreatic, and brain cancers, and the prognostic and therapeutic importance of NQO1 in oncology, probes to detect its cellular activity have been widely explored." (PMID 39120303, 2024).
cardiomyopathy (3 papers, 2019 to 2023). A disease of the heart muscle or myocardium proper. "Mechanistically, we found that the cardiac protection by Zn and BSE from IH-induced cardiomyopathy is associated with significant increases in MT- and Nrf2-mediated antioxidants, including NQO-1, SOD-2, and CAT." (PMID 31934264, 2019). "Similarly, our findings indicate that the anti-oxidant effects of both LGG and LGGs against IH-induced cardiomyopathy were mediated via activation of Nrf2 and its target genes (such as HO-1, NQO1, and CAT)." (PMID 31595164, 2019).
cervical squamous cell carcinoma (3 papers, 2014 to 2023). A squamous cell carcinoma arising from the cervical epithelium. "The localization of the NQO1 protein was determined in the SiHa cervical squamous cancer cell line using immunofluorescence (IF) staining, and immunohistochemical (IHC) staining performed on paraffin-embedded cervical SCC specimens from 177 patients." (PMID 24912939, 2014). "Moreover, we demonstrated that high expression of NQO1 in cervical squamous cell carcinoma patients was associated with lower disease-free survival (DFS) and 5-year OS rates compared with patients with low-level NQO1 expression." (PMID 25885439, 2015).
chronic prostatitis (3 papers, 2020 to 2023). An infectious or non-infectious chronic inflammatory process that affects the prostate gland. "Finally, NQO1 was identified as a key genetic link between ED and chronic prostatitis/chronic pelvic pain syndrome." (PMID 36846330, 2023).
emphysema (3 papers, 2014 to 2025). "Nrf-2/HO-1/NQO1 signaling activation led to attenuation in oxidative stress via downregulating ROS and NO production, thereby suppressing lung inflammation in the cigarette smoke extract-stimulated COPD and PPE-induced emphysema models." (PMID 40248092, 2025).
fibrosis (3 papers, 2023 to 2025). the formation of excess fibrous connective tissue in an organ or tissue in a reparative or reactive process. "Our results revealed a significant increase in the expression of both α-SMA and NQO1 in these fibrosis models." (PMID 40427075, 2025).
head and neck squamous cell carcinoma (3 papers, 2019 to 2023). A squamous cell carcinoma that arises from any of the following anatomic sites: lip and oral cavity, nasal cavity, paranasal sinuses, pharynx, larynx, and salivary glands. "Previous studies have demonstrated overexpression of NQO1 in various cancers including PDAC and a radiation tolerance group showed an up-regulated NQO1 expression in patients with head and neck squamous cell carcinoma." (PMID 32651227, 2020).
methemoglobinemia (3 papers, 2015 to 2023). An inherited or acquired condition characterized by abnormally increased levels of methemoglobin in the blood. "Strategies, such as using specific DNA repair inhibitors to lower the efficacious doses of NQO1 bioactivatable drugs, would significantly reduce the risk of hemolysis and Methemoglobinemia noted with ß-lap (ARQ761)." (PMID 26602448, 2015). "Such a strategy may lower dose-limiting methemoglobinemia (MH) caused by NQO1 bioactivatable drugs, while enabling, for the first time, tumor-selective use of DNA repair, specifically BER, inhibitors." (PMID 26602448, 2015). "Overall, our findings suggest that IP-DNQ effectively targets human NQO1+ tumors with fewer side effects (specifically, methemoglobinemia) in vivo." (PMID 38136388, 2023). "Most importantly, it offers broad NQO1-dependent, tumor-selectivity to BER inhibitors (e.g., MeOX), while eliminating dose-limiting hemolysis and Methemoglobinemia caused by higher ß-lap doses, otherwise required for efficacy." (PMID 26602448, 2015). "However, NQO1-bioactivatable drugs induce methemoglobinemia and hemolytic anemia at high doses." (PMID 32974194, 2020).
nasopharyngeal carcinoma (3 papers, 2010 to 2024). A carcinoma arising from the nasopharyngeal epithelium. "Although numerous studies have examined the association of the polymorphisms for CYP2E1, GSTP1, MPO and NQO1 genes with various tumors, very few have investigated the associations between variants of these genes and the risk of nasopharyngeal carcinoma." (PMID 20663217, 2010). "It has been shown that NQO1 expression is enhanced, while MMP9 and PCNA expression is downregulated with the declining deuterium concentration in nasopharyngeal carcinoma cells (NPCs)." (PMID 38732643, 2024). "In nasopharyngeal carcinoma (NPC), the significant down-regulation of Raf kinase inhibitor protein (RKIP) leads to the down-regulation of miR-450b-5p, thus activating NRF2/NQO1 signaling pathway and inhibiting ferroptosis process, which promotes NPC resistance to radiation." (PMID 36408273, 2022).
neuropathic pain (3 papers, 2019 to 2022). Chronic pain caused by damage to nerve fibers. "The inhibition of microglial activation and induction of the Nrf2/HO-1/NQO1 signaling pathway in the hippocampus and/or prefrontal cortex may explain the antidepressant effects of oltipraz during neuropathic pain." (PMID 31234342, 2019). "Our data also demonstrated the antidepressant properties of oltipraz in neuropathic pain, which may be mediated via inhibiting microglial activation in the hippocampus and triggering the Nrf2/HO-1/NQO1 signaling pathway in the prefrontal cortex and/or hippocampus." (PMID 31234342, 2019). "The fact that all of them reversed the antiallodynic and antihyperalgesic effects of HRW revealed the participation of the antioxidant enzymes (HO-1 and NQO1) and the KATP channels in the analgesic actions of HRW during neuropathic pain." (PMID 36139900, 2022).
oral cancer (3 papers, 2020 to 2021). "Accordingly, the antioxidant signaling gene expression for mRNA, including NFE2L2, GCLC, TXN, CAT, SOD1, HMOX1, and NQO1, was examined for POMx-incubated oral cancer cells." (PMID 34356350, 2021). "Similar to the present study, the mRNA expressions for several antioxidant genes (NFE2L2, GCLC, TXN, CAT, SOD1, HMOX1, and NQO1) were downregulated at 24 h POMx for three oral cancer cell lines." (PMID 34356350, 2021). "Consistently, we found that low concentrations of WFA induced mRNA expressions of NFE2L2, HMOX1, and NQO1 genes, which may lead to inhibitory migration of oral cancer cells." (PMID 32429564, 2020). "For example, sulforaphane can target Nrf2 and the Nrf2 target genes NQO1 and GCLC to prevent oral cancer, and a preclinical trail has been performed to study its chemopreventive activity for oral cancer." (PMID 33841137, 2021).
osteoarthritis (3 papers, 2019 to 2022). A noninflammatory degenerative joint disease occurring chiefly in older persons, characterized by degeneration of the articular cartilage, hypertrophy of bone at the margins and changes in the synovial membrane. "These outcomes were corroborated by other studies performed with H2 and with other compounds such as hydrogen sulfide donors and several antioxidants, which also activated the Nrf2/HO-1 and/or NQO1 pathway for alleviating chronic inflammatory, osteoarthritis, and neuropathic pain in rodents." (PMID 36358525, 2022). "In this study, we evaluated the effects of treatment with A-ITC and P-ITC on the protein levels of the antioxidant enzymes HO-1, NQO1, GSTM1, and GSTA1 in the hippocampus of animals with osteoarthritis pain." (PMID 31905764, 2019).
osteosarcoma (3 papers, 2018 to 2023). A usually aggressive malignant bone-forming mesenchymal neoplasm, predominantly affecting adolescents and young adults. "Quantitative real-time PCR analysis revealed that NQO1 and HO-1 were downregulated by oridonin in the osteosarcoma cells." (PMID 29323103, 2018). "Our results showed that oridonin inhibited the nuclear translocation of Nrf2 and downregulated Nrf2 target genes NQO1 and HO-1 in the osteosarcoma cells." (PMID 29323103, 2018). "The result showed that the NQO1 protein was localized to the cytosol of A-431 (epidermoid tumor cell line), U-251MG (Malignant glioma cell line), and U2OS (osteosarcoma cell line)." (PMID 37583897, 2023).
pneumonia (3 papers, 2017 to 2025). An acute, acute and chronic, or chronic inflammation focally or diffusely affecting the lung parenchyma, caused by an infection in one or both of the lungs (by bacteria, viruses, fungi, or mycoplasma.). "Conversely, the expression levels of IL10, SOD1, CAT, GPX1, and NQO1 were significantly lower in the pneumonia group than in the healthy control group." (PMID 40221769, 2025). "In our opinion, this is the first study to identify SNPs in antioxidant (SOD1, CAT, GPX1, NOS, HMOX1, and NQO1) and immunological (IL-1α, IL1B, IL6, TNF-α, IL10, LFA-1, CR2, IL17, IL13, DEFB123, SCART1, and ICAM1) genes as potential suspects for pneumonia resistance/susceptibility in Barki ewes." (PMID 40221769, 2025).